TPR (translocated promoter region, nuclear basket protein)
Description:
Component of the nuclear pore complex (NPC), a complex required for the trafficking across the nuclear envelope. Functions as a scaffolding element in the nuclear phase of the NPC essential for normal nucleocytoplasmic transport of proteins and mRNAs, plays a role in the establishment of nuclear-peripheral chromatin compartmentalization in interphase, and in the mitotic spindle checkpoint signaling during mitosis. Involved in the quality control and retention of unspliced mRNAs in the nucleus; in association with NUP153, regulates the nuclear export of unspliced mRNA species bearing constitutive transport element (CTE) in a NXF1- and KHDRBS1-independent manner. Negatively regulates both the association of CTE-containing mRNA with large polyribosomes and translation initiation. Does not play any role in Rev response element (RRE)-mediated export of unspliced mRNAs. Implicated in nuclear export of mRNAs transcribed from heat shock gene promoters; associates both with chromatin in the HSP70 promoter and with mRNAs transcribed from this promoter under stress-induced conditions. Modulates the nucleocytoplasmic transport of activated MAPK1/ERK2 and huntingtin/HTT and may serve as a docking site for the XPO1/CRM1-mediated nuclear export complex. According to some authors, plays a limited role in the regulation of nuclear protein export. Also plays a role as a structural and functional element of the perinuclear chromatin distribution; involved in the formation and/or maintenance of NPC-associated perinuclear heterochromatin exclusion zones (HEZs). Finally, acts as a spatial regulator of the spindle-assembly checkpoint (SAC) response ensuring a timely and effective recruitment of spindle checkpoint proteins like MAD1L1 and MAD2L1 to unattached kinetochore during the metaphase-anaphase transition before chromosome congression. Its N-terminus is involved in activation of oncogenic kinases.
Synonyms: MRT79
Tractability: Antibody: UniProt places it where antibodies can reach, with high confidence. PROTAC: ubiquitination databases record sites on it; its protein half-life has been measured.
Gene: Protein-coding gene on chromosome 1 (186,311,652 to 186,375,693, reverse strand). Ensembl gene ENSG00000047410.
Subcellular location: Nucleus; Nucleus membrane; Nucleus envelope; Nucleus, nuclear pore complex; Cytoplasm; Cytoplasm, cytoskeleton, spindle; Chromosome, centromere, kinetochore
Subcellular location (Human Protein Atlas): Nuclear membrane
Pathways (Reactome):
Disease: Defective TPR may confer susceptibility towards thyroid papillary carcinoma (TPC); HCMV Early Events; HCMV Late Events; NEP/NS2 Interacts with the Cellular Export Machinery; NS1 Mediated Effects on Host Pathways; Nuclear import of Rev protein; Rev-mediated nuclear export of HIV RNA; SARS-CoV-2 activates/modulates innate and adaptive immune responses; Signaling by ALK fusions and activated point mutants; Transport of Ribonucleoproteins into the Host Nucleus; Viral Messenger RNA Synthesis; Vpr-mediated nuclear import of PICs
Metabolism of RNA: Transport of Mature mRNA Derived from an Intronless Transcript; Transport of Mature mRNA derived from an Intron-Containing Transcript; Transport of the SLBP Dependant Mature mRNA; Transport of the SLBP independent Mature mRNA; snRNP Assembly; tRNA processing in the nucleus
Metabolism of proteins: SUMOylation of DNA damage response and repair proteins; SUMOylation of DNA replication proteins; SUMOylation of RNA binding proteins; SUMOylation of SUMOylation proteins; SUMOylation of chromatin organization proteins; SUMOylation of ubiquitinylation proteins
Metabolism: IP3 and IP4 transport between cytosol and nucleus; IP6 and IP7 transport between cytosol and nucleus; IPs transport between nucleus and cytosol; Regulation of Glucokinase by Glucokinase Regulatory Protein
Cell Cycle: Nuclear Pore Complex (NPC) Disassembly
Cellular responses to stimuli: Regulation of HSF1-mediated heat shock response
Immune System: ISG15 antiviral mechanism
Gene Ontology:
Molecular function: chromatin binding; dynein complex binding; heat shock protein binding; mitogen-activated protein kinase binding; mRNA binding; protein binding; protein homodimerization activity; protein-membrane adaptor activity; RNA binding; structural constituent of nuclear pore; tubulin binding
Biological process: cellular response to heat; mitotic spindle assembly checkpoint signaling; mRNA export from nucleus in response to heat stress; negative regulation of RNA export from nucleus; negative regulation of transcription by RNA polymerase II; negative regulation of translational initiation; nuclear matrix organization; nuclear pore complex assembly; nuclear pore organization; positive regulation of heterochromatin formation; positive regulation of intracellular protein transport; positive regulation of mitotic cell cycle spindle assembly checkpoint; positive regulation of protein import into nucleus; protein export from nucleus; protein import into nucleus; regulation of mitotic sister chromatid separation; regulation of mitotic spindle assembly; regulation of mRNA export from nucleus; regulation of protein export from nucleus; regulation of protein import into nucleus; regulation of protein localization; regulation of protein stability; response to epidermal growth factor; RNA export from nucleus; RNA import into nucleus; and 6 more
Cellular component: cytoplasm; cytoplasmic dynein complex; kinetochore; mitotic spindle; nuclear envelope; nuclear inclusion body; nuclear membrane; nuclear periphery; nuclear pore; nuclear pore nuclear basket; nucleus; nucleoplasm; spindle
Genetic constraint (gnomAD): Loss-of-function variants: 46 observed, 289.43 expected, observed/expected ratio (o/e) 0.16, 90% interval 0.12 to 0.2. The upper end of that interval is the gene's LOEUF score, 0.2, which puts it in group 1 of 6, group 1 being the genes least tolerant of losing a copy. Missense variants: 2,143 observed, 2,713 expected, observed/expected ratio (o/e) 0.79, 90% interval 0.76 to 0.82. Synonymous variants: 936 observed, 910.78 expected, observed/expected ratio (o/e) 1.03, 90% interval 0.97 to 1.09.
Homologues: Orthologues: chimpanzee TPR (99% identical), dog TPR (98% identical), pig TPR (97% identical), macaque TPR (97% identical), rabbit TPR (97% identical), rat Tpr (94% identical), guinea pig TPR (94% identical), mouse Tpr (94% identical), tropical clawed frog tpr (70% identical), zebrafish tprb (59% identical), zebrafish tpra (58% identical), Drosophila melanogaster Mgtor (23% identical).
Diseases named in the same sentence as TPR in open-access papers:
TPR is named in the same sentence as 43 diseases in open-access papers, as found by Europe PMC text mining. Sharing a sentence is not in itself a finding about the gene and the disease. The quoted sentences say what the papers report.
breast carcinoma (4 papers, 2014 to 2025). "In conclusion, our results suggest that LINC01705 is implicated in the progression of breast cancer via competitively binding to miR-186-5p as a competing endogenous RNA (ceRNA), thereby regulating TPR expression." (PMID 32849791, 2020). "We first investigated the interactions of isolated human platelets and MDA-MB-231-RFP cells ex vivo to establish the role of TPr in platelet adhesion with breast cancer cells." (PMID 41233835, 2025). "Next, we established orthotopic mammary tumors with TBXA2R-deleted 4T1 tumor cells (TPr KO 4T1 cells) and commenced treatment with ifetroban under the same protocol." (PMID 41233835, 2025). "Collectively, this study confirmed that LINC01705 is implicated in the progress of breast cancer via sponging miR-186-5p, thereby mediating the expression of the TPR, providing a novel perspective for the study of the pathogenesis of breast cancer." (PMID 32849791, 2020). "Thereafter, qRT-PCR was utilized to determine TPR expression in breast cancer cell lines and tissues where the mRNA levels of TPR were remarkably elevated." (PMID 32849791, 2020). "Our study also revealed TPR overexpression in breast cancer cells and tissues and its expression level is closely related to cell proliferation and migration of BT-549 and MCF-7 cells." (PMID 32849791, 2020). "In summary, LINC01705 acts as a competitive endogenous RNA to regulate TPR expression via sponging miR-186-5p, thereby regulating the progression of breast cancer." (PMID 32849791, 2020). "Overexpression of wild-type LINC01705 enhanced TPR expression in breast cancer cells, as shown using both qRT-PCR and Western blotting." (PMID 32849791, 2020). "We next detected changes in TPR expression in breast cancer cells after altering LINC01705 or miR-186-5p expression to explore whether TPR was regulated by LINC01705 through targeting miR-186-5p." (PMID 32849791, 2020). "To further improve the cytotoxic activity of Antp-TPR toward cancer cells, we investigated the effect of a Hsp70-targeted peptide, which was made cell-permeable by adding the polyarginine with a linker sequence, on the cytotoxic activity of Antp-TPR in breast cancer cell lines." (PMID 25159299, 2014). "However, the cytotoxic activity of Antp-TPR toward breast cancer cells was effectively increased in a concentration-dependent manner in the presence of R11-Hsp70." (PMID 25159299, 2014). "Thus, it was found that the combination treatment of Antp-TPR with R11-Hsp70 could induce effective cytotoxic activity toward breast cancer cell lines used in this study, which have different characteristic such as genetic alterations or sensitivity for molecular targeted drugs." (PMID 25159299, 2014).
lung carcinoma (4 papers, 2014 to 2025). "It is possible that overexpression of TPR in lung cancer cells causes mislocalization of its interaction partners such as NXF1, leading to dysregulated nuclear export of RNAs and proteins related to cancer development." (PMID 34793452, 2021). "In accordance with this result, western blotting of 8 pairs of tumor and adjacent tissues from lung cancer patients confirmed that the protein level of TPR was higher in tumor tissues." (PMID 34793452, 2021). "We found that lung cancer patients with high TPR mRNA had shorter overall survival and progression-free survival." (PMID 34793452, 2021). "To further explore the clinical significance of TPR expression, we carried out a compiled analysis of TPR mRNA abundance in tumor and adjacent tissues from lung cancer patients using independent datasets GSE7670, GSE10072, GSE19188 and GSE31210." (PMID 34793452, 2021). "To analyze the correlation between TPR mRNA level and different clinicopathological features, we queried three independent lung cancer patient datasets: GSE4573, GSE8894 and GSE12667." (PMID 34793452, 2021). "We find that TPR is overexpressed in lung cancer tissues and correlated with poor prognosis, whereas down-regulation of TPR inhibits tRNA nuclear export, protein synthesis and cell growth." (PMID 34793452, 2021). "Our finding of their functions in tRNA trafficking in lung cancer cells suggests that TPR and NXF1 orchestrate the nuclear export of different forms of RNAs to promote protein synthesis." (PMID 34793452, 2021). "Consistently, knockdown of TPR inhibits tRNA nuclear export, protein synthesis and cell growth in lung cancer cell lines." (PMID 34793452, 2021). "We then show that human TPR plays the same role in lung cancer cells, which have elevated expression of TPR that are correlated with unfavorable prognosis in patients." (PMID 34793452, 2021). "TPR-related mutations, including TPR-ALK fusions, may initiate lung cancer and serve as potential biomarkers for immunotherapy." (PMID 40136480, 2025). "Also, a colony formation experiment demonstrated that knockdown of TPR strongly inhibited the proliferation of three of the four lung cancer cell lines." (PMID 34793452, 2021). "In addition, western blotting showed that TPR was elevated in A549, H322, H460 and H1299 lung cancer cells compared to normal human lung fibroblasts (HLF)." (PMID 34793452, 2021). "To investigate whether TPR promotes the growth of lung cancer cells, we transiently knocked down the protein using three different siRNAs in A549, H322, H460 and H1299 cells." (PMID 34793452, 2021). "Our experiments indicate that TPR normally promotes tRNA nuclear export in lung cancer cells." (PMID 34793452, 2021). "This implies that NXF1 plays a less dominant role than TPR in the tumorigenesis of lung cancer." (PMID 34793452, 2021). "We found that, like mRNA levels, the expression of TPR protein was elevated in lung cancer cells." (PMID 34793452, 2021). "Considering that the yeast orthologs of TPR coordinated the coupled transcription and nuclear export of pre-tRNA for protein synthesis in yeast, we hypothesized that elevated expression of TPR facilitated the nuclear export of tRNAs in lung cancer cells." (PMID 34793452, 2021). "The viability and proliferation capacity of lung cancer cells were dramatically reduced when NXF1 was knocked down, similar to the effects of TPR knockdown." (PMID 34793452, 2021). "In particular, NTRK1 has been found to fuse with tropomyosin in colon cancer, TPM3, TPR, and TFG in thyroid cancer, and MPRIP and CD74 in lung cancer." (PMID 24647444, 2014). "We used immunoblot to examine whether knockdown of TPR alters the expression of proteins involved in NPC functions, and found that XPO1 level was decreased when TPR was knocked down in A549 lung cancer cells." (PMID 34793452, 2021).
lung carcinoma (continued). "However, unlike TPR, the mRNA and protein level of NXF1 was not increased in tumor tissues from lung cancer patients, and knockdown of TPR did not down-regulate the expression of NXF1." (PMID 34793452, 2021).
ependymoma (3 papers, 2020 to 2022). A WHO grade II, slow growing tumor of children and young adults, usually located intraventricularly. "A study showed that high expression of TPR is associated with ependymoma and TPR may act as a biomarker for ependymoma." (PMID 32849791, 2020). "The authors found that high expression of TPR was associated with increased HSF1 and HSPA/HSP70 expression in ependymoma patients and showed that MTOR inhibition by rapamycin therapeutically suppressed TPR expression and reduced tumor size in an ependymoma mouse xenograft model." (PMID 36197606, 2022). "Particularly, TPR silencing induces nuclear membrane blebbing, hypothesizing that high levels of TPR could prevent the so-called nucleophagy—i.e., selective autophagy degradation of nuclear components —favouring tumorigenesis in ependymoma." (PMID 33803216, 2021).
gastric cancer (3 papers, 2017 to 2023). A primary or metastatic malignant neoplasm involving the stomach. "Further, levels of the remaining two genes, TPR and RNABP2, were higher in gastric cancer tissue, but the differences were not significant (p > 0.01)." (PMID 38259281, 2023).
hepatocellular carcinoma (3 papers, 2021 to 2023). A malignant tumor that arises from hepatocytes. "The frequent trend of CN-gain of TPR and ODR4 in chromosome 1q may indicate that CN-gain of TPR and ODR4 plays a role in the progression of DPHCC, while chromosome 11 has little effect on the transformation of this hepatocellular carcinoma subtype." (PMID 33854600, 2021).
colon cancer (2 papers, 2014 to 2018). "Together, these morphological and biochemical findings suggest that GSK3β participates in proper localization and function of the mitotic mediators dynein and TPR to sustain mitosis for colon cancer cell propagation." (PMID 29568361, 2018).
colorectal adenocarcinoma (2 papers, 2018 to 2020). The most common type of colorectal carcinoma. "Kaplan-Meier analysis of TCGA cohorts revealed that TPR overexpression was significantly correlated with poorer outcome of colorectal adenocarcinoma patients (Log-rank test, P = 0.02)." (PMID 29568361, 2018).
colorectal cancer (2 papers, 2021 to 2022). A primary or metastatic malignant neoplasm that affects the colon or rectum. "Moreover, a recent study in colorectal cancer cells reported that rapid depletion of TPR by the auxin-induced degron (AID) system not only disrupted association of the TREX-2 complex subunits to NPCs, but also resulted in pronounced changes in RNA transcription and export." (PMID 34793452, 2021).
liver cancer (2 papers, 2022 to 2023). An epithelial or non-epithelial malignant neoplasm that arises from the liver.
pancreatic cancer (2 papers, 2012 to 2022). "In fact, we previously reported that a 1 mg/kg dosage of Antp-TPR peptide displayed a significant antitumor activity in a xenograft model of human pancreatic cancer in mice." (PMID 22913813, 2012).
papillary thyroid cancer (2 papers, 2014 to 2024). "In up to 12% of papillary thyroid cancer patients, the 3′ exons of NTRK1 with the kinase domain had been found to fuse with the 5′ exons of various thyroid-expressed genes (TPM3, TPR, TFG) in frame." (PMID 24647444, 2014).
sarcoma (2 papers, 2022 to 2024). A usually aggressive malignant neoplasm of the soft tissue or bone. "Additionally, fusions involving the translocated promoter region protein (TPR) gene have been implicated in various sarcomas including osteosarcoma." (PMID 38562379, 2024).
thyroid cancer (2 papers, 2014 to 2024). "The GO enrichment and KEGG pathway of TPR was mainly involved in RNA transport, nuclear, response to heat stress, mitosis, and thyroid cancer, RNA transport, pathways in cancer, amyotrophic lateral sclerosis, respectively." (PMID 38754841, 2024).
triple-negative breast carcinoma (2 papers, 2025 to 2026). An invasive breast carcinoma which is negative for expression of estrogen receptor (ER), progesterone receptor (PR), and human epidermal growth factor receptor 2 (HER2). "Here, we repurpose the thromboxane A2-prostanoid receptor (TPr) inhibitor, ifetroban, to block platelet-tumor cell interactions and reduce metastasis in models of triple negative breast cancer (TNBC)." (PMID 41233835, 2025). "Ifetroban, a selective thromboxane A2-prostanoid receptor (TPr) antagonist, robustly inhibits triple negative breast cancer (TNBC) metastasis by modulating the TXA2 signaling pathway." (PMID 41233835, 2025). "Finally, immunohistochemical analysis reveals elevated TPR phosphorylation in serous ovarian carcinoma and heterogeneous phosphorylation patterns in triple-negative breast cancer, two tumor types frequently characterized by MAPK pathway hyperactivation." (PMID 42031697, 2026).
acute monocytic leukemia (1 paper, 2023). Acute monoblastic leukemia (AML-M5), is one of the most common subtypes of acute myeloid leukemia (AML) that is either comprised of more than 80% of monoblasts (AML-M5a) or 30-80% monoblasts with (pro)monocytic differentiation (AML-M5b). "After transduction with lentiviral particles coding for the different CAR constructs Jurkat-TPR was cocultured with MOLM-13 cells, an AML cell line expressing CD33 established from the peripheral blood of an acute monocytic leukemia relapsed patient." (PMID 37795087, 2023).